PTPRQ (protein tyrosine phosphatase receptor type Q)
Description:
Dephosphorylates phosphatidylinositol phosphates, such as phosphatidylinositol 3,4,5-trisphosphate (PIP3) and phosphatidylinositol 3,5-diphosphates, with preference for PIP3. Phosphate can be hydrolyzed from the D3 and D5 positions in the inositol ring. Has low tyrosine-protein phosphatase activity in vitro; however, the relevance of such activity in vivo is unclear (By similarity). Plays an important role in adipogenesis of mesenchymal stem cells (MSCs). Regulates the phosphorylation state of AKT1 by regulating the levels of PIP3 in MSCs and preadipocyte cells. Required for hair bundle maturation, a process that enables hair cells to detect and transmit sound and balance signals effectively, therefore affecting auditory function. May act by regulating the level of phosphatidylinositol 4,5-bisphosphate (PIP2) level in the basal region of hair bundles (By similarity).
Synonyms: R-PTP-Q; DFNA73; DFNB84; DFNB84A; PTPGMC1
Gene: Protein-coding gene on chromosome 12 (80,402,178 to 80,680,273, forward strand). Ensembl gene ENSG00000139304.
Subcellular location: Cell projection, stereocilium; Apical cell membrane; Basal cell membrane
Subcellular location (Human Protein Atlas): Cytosol
Genetic constraint (gnomAD): Loss-of-function variants: 172 observed, 207.52 expected, observed/expected ratio (o/e) 0.83, 90% interval 0.73 to 0.94. The upper end of that interval is the gene's LOEUF score, 0.94, which puts it in group 3 of 6, group 1 being the genes least tolerant of losing a copy. Missense variants: 2,384 observed, 2,355.4 expected, observed/expected ratio (o/e) 1.01, 90% interval 0.98 to 1.05. Synonymous variants: 789 observed, 798.29 expected, observed/expected ratio (o/e) 0.99, 90% interval 0.93 to 1.05.
Gene-disease validity (ClinGen):
ClinGen rates the evidence that PTPRQ causes each of these diseases.
hearing loss, autosomal recessive (autosomal recessive): Definitive.
Homologues: Orthologues: macaque PTPRQ (97% identical), rabbit PTPRQ (91% identical), chimpanzee PTPRQ (91% identical), dog PTPRQ (91% identical), pig PTPRQ (89% identical), rat Ptprq (87% identical), mouse Ptprq (87% identical), guinea pig PTPRQ (85% identical), tropical clawed frog PTPRQ (59% identical). Paralogues in human: SDK2 (12% identical), SDK1 (11% identical), NRCAM (10% identical), DCC (10% identical), IGSF10 (10% identical), L1CAM (10% identical), NEO1 (10% identical), HMCN2 (9% identical), MXRA5 (9% identical), CHL1 (9% identical), ROBO1 (9% identical), ROBO2 (9% identical), and 24 more.
Diseases named in the same sentence as PTPRQ in open-access papers:
PTPRQ is named in the same sentence as 30 diseases in open-access papers, as found by Europe PMC text mining. Sharing a sentence is not in itself a finding about the gene and the disease. The quoted sentences say what the papers report.
hearing loss (19 papers, 2015 to 2025). "The WGS analysis resulted in 4.86 million detected variants on average, filtered to 223 thousand rare variants, 1.05 thousand rare variants in hearing loss genes and 23 rare variants in PTPRQ." (PMID 40165225, 2025). "Beyond the morphological changes caused by the absence of CLIC5, its deficiency has been shown to disrupt the localization of proteins such as RDX, TPRN, and PTPRQ, which are linked to hearing loss." (PMID 40859056, 2025). "Despite progress in gene therapy for hearing loss, research on PTPRQ and its involvement in auditory impairment is limited, highlighting the need for comprehensive functional studies on PTPRQ variants." (PMID 39205941, 2024). "These variants lead to the production of truncated PTPRQ proteins, which are likely contributors to hearing loss." (PMID 39205941, 2024). "It is highly unlikely that the missense pathogenic variant observed in PTPRQ was the cause of hearing loss." (PMID 35951321, 2022). "PTPRQ mutations were identified to be related to congenital hearing loss and vestibular dysfunction syndrome." (PMID 33242228, 2021). "The finding strongly reinforces the inclusion of PTPRQ to the small set of genes leading to both autosomal recessive and dominant hearing loss." (PMID 31655630, 2019). "Our data here further prove the important role of PTPRQ in auditory function and provide more information for the further mechanism research of PTPRQ-related hearing loss." (PMID 29849575, 2018). "Next, these variants were compared to reported non-syndromic hereditary hearing loss genes, then two mutations (c.3125 A>G and c.5981 A>G) were found in a previously reported deafness-related gene, PTPRQ." (PMID 25919374, 2015). "However, unlike us, the child’s parents were consanguineous and had a mutation in the PTPRQ gene, which has been associated with nonsyndromic hearing loss." (PMID 38915054, 2024). "Our findings enhance the understanding of genotype-phenotype correlations in PTPRQ-related hearing loss and may inform clinical management and genetic counseling." (PMID 39205941, 2024). "A total of 32 pathogenic PTPRQ variants associated with hearing loss have been reported." (PMID 39205941, 2024). "More than thirty mutations of PTPRQ have been identified in patients with hearing loss." (PMID 33478437, 2021). "In addition, the protein tyrosine phosphatase receptor type Q (PTPRQ) gene has been identified in nonsyndromic hearing loss patients with autosomal recessive or autosomal dominant inherited patterns." (PMID 33478437, 2021). "Previous studies have proven that homozygous mutation of PTPRQ may lead to nonsyndromic hearing loss." (PMID 33478437, 2021). "However, the detailed clinical features of PTPRQ-associated hearing loss (HL) remain unclear." (PMID 38674423, 2024). "Another member of this family, protein tyrosine phosphatase, receptor type, Q gene (PTPRQ), is responsible for the dominant form (DFNA73) and recessive form (DFNB84) of nonsyndromic hearing loss in humans." (PMID 36140322, 2022). "PTPRQ: PTPRQ (MIM 603317; 12q21.3) is a known cause of AD (MIM 617663) or AR (MIM 613391) nonsyndromic hearing loss in families and probands with multiple ethnicities, which may be variable in clinical presentation." (PMID 33924653, 2021). "The mechanism we present here, where GRXCR2 restricts taperin from entering the stereocilia shaft, may also explain the morphological defects and hearing loss caused by mutations of CLIC5, radixin, PTPRQ, MYO6, Fam65b, or other components located at the basal region of stereocilia." (PMID 30380417, 2018). "Our results suggest that the mutational spectrum of PTPRQ is not well covered by standard WES and that PTPRQ-associated hearing loss may be more frequent than previously thought." (PMID 40165225, 2025).
deafness (17 papers, 2012 to 2024). An inherited or acquired condition characterized by the complete loss of the ability to hear from one or both ears. "In conclusion, our study has identified two novel variants in the PTPRQ gene associated with deafness." (PMID 39205941, 2024). "Both cases were attributed to variants in the PTPRQ gene, which is predominantly associated with postlingual deafness and follows an autosomal recessive inheritance pattern (DFNB84A type)." (PMID 39205941, 2024). "Given the recessive inheritance pattern observed in this family, the top five genes were identified, with the PTPRQ gene showing a strong association with deafness." (PMID 39205941, 2024). "It should be noted that, although PTPRQ is also expressed in many other cilia-bearing cells, patients with PTPRQ disease variants thus far only present with deafness and vestibular dysfunction, pointing to functional redundancy in the unaffected tissues." (PMID 36755664, 2022). "Rare variants in the PTPRQ gene are known to cause deafness in the homozygous recessive or heterozygous dominant state." (PMID 35951321, 2022). "A missense alteration in a FNIII repeat in the PTPRQ transmembrane phosphatase has been linked to deafness; how this mutation affects PTPRQ function is not yet known." (PMID 29440357, 2018). "Mutations in PTPRQ are associated with deafness in humans due to defects of stereocilia in hair cells." (PMID 25919374, 2015). "PTPRQ mutations may alter the morphology and stereocilia and further lead to the gradual loss of cochlear hair cells and subsequent deafness." (PMID 33478437, 2021). "In addition to GRXCR2 and taperin, several proteins linked to deafness are concentrated at or near the stereocilia base, including Fam65b, PTPRQ, CLIC5, radixin, and PDZD7." (PMID 30380417, 2018). "PTPRQ mutations are rare causes of recessive deafness as there are only two reports worldwide." (PMID 25919374, 2015). "PTPRQ mutant mice exhibit malformations in shaft connectors and immature cochlear hair bundles, leading to deafness." (PMID 39205941, 2024). "Among the 98 deafness-related genes detected in this study, SLC26A4 (62.7%, 32/51), MYO15A (63.6%, 14/22), OTOF (40.0%, 4/10) and PTPRQ (75.0%, 3/4) contained intronic variants." (PMID 36597107, 2023). "RDX, protein tyrosine phosphatase receptor Q (PTPRQ), and TPRN which are associated with deafness, were mislocalized in fused stereocilia of CLIC5A-deficient mice." (PMID 36035115, 2022). "In this study, 48.5% (16/33) families were detected the pathogenic variants in eight known deafness genes, including 10 novel variants identified in TMPRSS3 (MIM 605551), MYO15A (MIM 602666), TMC1 (MIM 606706), ADGRV1 (MIM 602851), and PTPRQ (MIM 603317)." (PMID 31379920, 2019). "PTPRQ encodes a member of the type III receptor-like protein-tyrosine phosphatase family, and its mutations may cause autosomal recessive deafness." (PMID 34454438, 2021). "The known deafness genes with variants detected in this study were GJB2 (MIM 121011; 21.2%), TMPRSS3 (MIM 605551; 6.1%), MYO15A (MIM 602666; 6.1%), TMC1 (MIM 606706; 3%), ADGRV1 (MIM 602851; 3%), PTPRQ (MIM 603317; 3%), SLC26A4 (MIM 605646; 3%), and OTOF (MIM 603681; 3%)." (PMID 31379920, 2019). "In the two simplex families, compound heterozygous variants c.5426+1G > A and c.6087-3T > G in PTPRQ were identified in the proband of Family E and homozygous variant c.164+5G > A in USH1G in Family F. No other candidate variants in known deafness genes have been identified." (PMID 34956325, 2021).
Autosomal Recessive Hearing Loss (4 papers, 2015 to 2022). "In 2018 the first heterozygous PTPRQ variant has been implicated in the development of autosomal dominant non-syndromic hearing loss (ADNSHL) in a German family." (PMID 31655630, 2019).
sensorineural hearing loss (3 papers, 2015 to 2024). "Variants in the PTPRQ gene have been implicated in hereditary sensorineural hearing loss." (PMID 39205941, 2024). "Mutations in the PTPRQ gene have been reported to cause hereditary sensorineural hearing loss." (PMID 35899188, 2022).
Obesity (2 papers, 2013 to 2023). Accumulation of substantial excess body fat. "It was also demonstrated that the overexpression of PTPRQ caused the differentiation of mesenchymal stem cells (MSCs) into adipocytes, which leads to the pathogenesis of obesity." (PMID 23981594, 2013). "Furthermore, PIK3C2G, FIBIN, CHRNA1, NPNT, MEOX1, and POU2F2 linked obesity and lung cancer, while PTPRQ, SSUH2, CILP2, CDH2, ABCA12, CPXM1, and L1CAM linked hypertension and lung cancer." (PMID 36685671, 2023). "Although PTPRQ was known to be involved in the pathogenesis of obesity, no small-molecule inhibitor has been reported so far." (PMID 23981594, 2013).
Vertigo (2 papers, 2018 to 2022). An abnormal sensation of spinning while the body is actually stationary. "The patients with PTPRQ mutations always had vertigo or dizziness." (PMID 29849575, 2018).
Arrhythmia (1 paper, 2023). Any cardiac rhythm other than the normal sinus rhythm. "PTPRQ, PLEKHB2, IL1RAPL1, and EXT1 are predicted to be involved in biological processes such as heart and large blood vessel development, as well as cardiac phenotypes such as arrhythmias, valve diseases, and cardiomyopathy." (PMID 37684230, 2023).
autism (1 paper, 2022). Persistent deficits in social interaction and communication and interaction as well as a markedly restricted repertoire of activity and interest as well as repetitive patterns of behavior. "For example, in all our severe autism samples (and none from the mild autism grouping) a common affected gene (PTPRQ) is found in all four clinical sub-phenotypes which is linked in literature to auditory impairment." (PMID 36117207, 2022).
lung adenocarcinoma (1 paper, 2022). A carcinoma that arises from the lung and is characterized by the presence of malignant glandular epithelial cells. "In contrast, several PTPs were identified as the suppressive genes in cancer, such as PTPRZ1 in BRCA and PTPRQ in lung adenocarcinoma (LUAD)." (PMID 36341348, 2022).
metastatic tumors (1 paper, 2023). "Increased expression of PTPRQ was observed in metastatic tumors from mice." (PMID 37445641, 2023).
cancer (4 papers, 2017 to 2023). A tumor composed of atypical neoplastic, often pleomorphic cells that invade other tissues. "The R3 subgroup of RPTPs includes density-enhanced phosphatase 1 (DEP-1), vascular endothelial protein tyrosine phosphatase (VE-PTP), stomach cancer-associated protein tyrosine phosphatase 1 (SAP-1), glomerular epithelial protein 1 (GLEPP1), and receptor-type protein tyrosine phosphatase Q (PTPRQ)." (PMID 28926625, 2017).
cardiovascular disease (1 paper, 2022). "Variants near PTPRQ reached genome-wide significance to cIMT among young PWH; this gene encodes a member of the type III receptor-like protein-tyrosine phosphatase family, playing roles in cellular proliferation and differentiation, which might have a link to cardiovascular disease." (PMID 36539828, 2022).
PTPRQ also shares sentences with these, for which no sentence is quoted: Townes-Brocks syndrome (2 papers); Adult onset (1); Alzheimer disease (1); Ataxia (1); cardiomyopathy (1); cerebellar ataxia (1); epilepsy (1); External ophthalmoplegia (1); Hearing impairment (1); heart disease (1); Hypertension (1); injury (1); lung carcinoma (1); myopathy (1); nonsyndromic hearing loss (1); Parkinson disease (1); Tinnitus (1); tumor (1).